SIN3B (SIN3 transcription regulator family member B)
Description:
Acts as a transcriptional repressor. Interacts with MXI1 to repress MYC responsive genes and antagonize MYC oncogenic activities. Interacts with MAD-MAX heterodimers by binding to MAD. The heterodimer then represses transcription by tethering SIN3B to DNA. Also forms a complex with FOXK1 which represses transcription. With FOXK1, regulates cell cycle progression probably by repressing cell cycle inhibitor genes expression. As part of the SIN3B complex represses transcription and counteracts the histone acetyltransferase activity of EP300 through the recognition H3K27ac marks by PHF12 and the activity of the histone deacetylase HDAC2. SIN3B complex is recruited downstream of the constitutively active genes transcriptional start sites through interaction with histones and mitigates histone acetylation and RNA polymerase II progression within transcribed regions contributing to the regulation of transcription.
Synonyms: KIAA0700
Tractability: Small molecule: a structure with a bound ligand is known. Antibody: the Human Protein Atlas places it where antibodies can reach. PROTAC: UniProt records ubiquitination sites on it; ubiquitination databases record sites on it; its protein half-life has been measured.
Gene: Protein-coding gene on chromosome 19 (16,829,387 to 16,880,355, forward strand). Ensembl gene ENSG00000127511.
Subcellular location: Nucleus
Subcellular location (Human Protein Atlas): Nucleoplasm; Plasma membrane
Pathways (Reactome):
Gene expression (Transcription): NoRC negatively regulates rRNA expression; RUNX1 regulates genes involved in megakaryocyte differentiation and platelet function
Cellular responses to stimuli: Cytoprotection by HMOX1
Metabolism: Regulation of lipid metabolism by PPARalpha
Gene Ontology:
Molecular function: protein binding; transcription corepressor activity; chromatin binding
Biological process: negative regulation of cell migration; negative regulation of transcription by RNA polymerase II; negative regulation of transcription initiation by RNA polymerase II; negative regulation of DNA-templated transcription; regulation of DNA-templated transcription
Cellular component: nucleoplasm; nucleus; Sin3-type complex; autosome; cytoplasm; X chromosome; XY body; Y chromosome
Genetic constraint (gnomAD): Loss-of-function variants: 19 observed, 113.59 expected, observed/expected ratio (o/e) 0.17, 90% interval 0.12 to 0.25. The upper end of that interval is the gene's LOEUF score, 0.25, which puts it in group 1 of 6, group 1 being the genes least tolerant of losing a copy. Missense variants: 1,065 observed, 1,573.2 expected, observed/expected ratio (o/e) 0.68, 90% interval 0.64 to 0.71. Synonymous variants: 640 observed, 658.27 expected, observed/expected ratio (o/e) 0.97, 90% interval 0.91 to 1.04.
Homologues: Orthologues: chimpanzee SIN3B (99% identical), macaque SIN3B (99% identical), pig SIN3B (96% identical), dog SIN3B (95% identical), mouse Sin3b (90% identical), guinea pig SIN3B (83% identical), tropical clawed frog sin3b (74% identical), zebrafish sin3b (67% identical), Drosophila melanogaster Sin3A (44% identical), Caenorhabditis elegans sin-3 (22% identical). Paralogues in human: SIN3A (54% identical).
Diseases named in the same sentence as SIN3B in open-access papers:
SIN3B is named in the same sentence as 20 diseases in open-access papers, as found by Europe PMC text mining. Sharing a sentence is not in itself a finding about the gene and the disease. The quoted sentences say what the papers report.
breast carcinoma (5 papers, 2016 to 2024). "Here, we show that individual knockdown of SIN3A causes an increase, whereas knockdown of SIN3B causes a decrease in breast cancer invasion and metastatic potential." (PMID 27780928, 2016). "To explore the potential of SIN3B as a therapeutic target in other cancers, we analyzed transcriptomic data from human colon cancer, lung cancer, and breast cancer obtained from the CPTAC database." (PMID 39316363, 2024). "In contrast, SIN3B knockdown substantially decreased breast cancer cell invasion and resulted in reduced metastatic potential." (PMID 29665841, 2018). "We compared SIN3A and SIN3B gene expression with relapse-free survival of patients with breast cancer." (PMID 27780928, 2016). "Future work will be necessary to fully understand specific targets regulated by SIN3A and SIN3B and in what context or molecular subtype of breast cancer." (PMID 27780928, 2016). "HTRA1 was upregulated on the SIN3B knockdown gene list and high HTRA1 expression is associated with overall and disease-free survival in patients with breast cancer." (PMID 27780928, 2016). "The results suggest that SIN3B is required for and is a promoter of breast cancer progression and metastasis, and further suggest that SIN3A is a metastasis suppressor." (PMID 27780928, 2016). "High expression of either SIN3A or SIN3B correlated with longer relapse-free survival in all breast cancers (hazard ratios = 0.58 and 0.49; logrank P = 7.8e-10 and < 1e-16 respectively for SIN3A and SIN3B)." (PMID 27780928, 2016). "Although we have not validated these gene sets by analyzing the expression of individual genes, the data support our hypothesis that SIN3A and SIN3B have differential functions in breast cancer progression." (PMID 27780928, 2016). "Additionally, we analyzed microarray data sets to identify correlations of SIN3A and SIN3B expression with survival in patients with breast cancer." (PMID 27780928, 2016). "Our data supports SIN3A as a suppressor of breast cancer progression and metastasis, whereas SIN3B may be a promoter." (PMID 27780928, 2016). "Together, these results demonstrate differential gene regulation by SIN3A and SIN3B that may help to explain reasons for the functional differences in breast cancer." (PMID 27780928, 2016). "We hypothesized that SIN3A and SIN3B play differential roles during breast cancer progression." (PMID 27780928, 2016). "When all breast cancer subtypes were considered, longer relapse-free survival of patients correlated with high expression of either SIN3A or SIN3B." (PMID 29665841, 2018). "Together, these results demonstrate differential regulation of breast cancer cell invasion by SIN3A and SIN3B." (PMID 27780928, 2016). "This is consistent with recent studies demonstrating inhibition of breast cancer invasion using SIN3 interacting domain decoy peptides and small molecule inhibitors of SIN3 that inhibit both SIN3A and SIN3B." (PMID 27780928, 2016). "Conversely, in the lung cancer and breast cancer cohorts, SIN3B did not exhibit any correlation with CXCL9/10/11 or CD8A." (PMID 39316363, 2024). "To determine whether the SIN3 complex mediates breast cancer progression, we knocked out both SIN3A and SIN3B proteins with the CRISPR/Cas9 technique in MDA-MB-231 cells." (PMID 37655663, 2023). "The differential roles of SIN3A and SIN3B in breast cancer progression is not completely unexpected considering that knockout mice for either Sin3A or Sin3B is embryonic lethal at different stages of development." (PMID 27780928, 2016). "Our data shows that high expression of either SIN3A or SIN3B correlates with longer relapse-free survival of patients with breast cancer when samples were not stratified." (PMID 27780928, 2016).
breast carcinoma (continued). "Very different it is the case of SIN3B (SIN3 transcription regulator family member B), a well known protein that interacts with MYC (MYC proto-oncogene, BHLH transcription factor), which was observed promoting cancer progression and metastasis in breast cancer in accordance with our data." (PMID 31159827, 2019). "However, specific roles for SIN3A and SIN3B in breast cancer progression have not been characterized." (PMID 27780928, 2016).
colorectal cancer (2 papers, 2024). A primary or metastatic malignant neoplasm that affects the colon or rectum. "In the human colorectal cancer (CRC) cohort, SIN3B expression levels were significantly negatively correlated with CXCL9/10/11 as well as CD8A, GzmA, and GzmB." (PMID 39316363, 2024).
metastatic disease (2 papers, 2012 to 2014). "Recently, however, comparative mutational genomic analysis of samples taken from a patient with ENB at the time of initial presentation and following recurrent metastatic disease showed new acquired mutations in KDR, MYC, SIN3B, and NLRC4 genes with disease progression." (PMID 24672769, 2014). "However, in the original surgical resection specimen (prior to evidence of metastatic disease), mutations in KDR, MYC, SIN3B, and NLRC4 genes were not present, suggesting that these were acquired with disease progression and/or as a result of post-treatment effects." (PMID 22649506, 2012).
pancreatic cancer (2 papers, 2020 to 2024). "Moreover, in an orthotopic pancreatic cancer mouse model, Sin3B deficiency significantly impeded the progression of pancreatic cancer, consequently prolonging the survival of tumor‐bearing mice." (PMID 39316363, 2024). "Based on the differences observed between in vivo and in vitro experiments, as well as previous reported CRISPR screening result, we hypothesized that the inhibitory effect Sin3B loss on pancreatic cancer might rely on anti‐tumor immunity." (PMID 39316363, 2024). "Remarkably, a similar trend was observed in a mouse model of orthotopic pancreatic cancer, where Sin3B loss significantly augmented CD8+ T cell infiltration, alongside heightened cytotoxicity against tumor cells, as evidenced by the upregulation of IFNγ and GzmB." (PMID 39316363, 2024). "The mammalian ortholog of Rpd3S/Clr6-CII is the Sin3B complex, which localizes to transcribed genes and is a potential therapeutic target in pancreatic cancer." (PMID 32496538, 2020). "Therefore, our study provides a novel perspective and insight into the role of SIN3B in pancreatic tumor development." (PMID 39316363, 2024). "Moreover, Sin3A loss leads to decreased expression of Cxcl9, Ifng, and Tnfa in pancreatic tumor tissues, suggesting that SIN3A plays a distinct role in the regulation of the TIME, differing from that of SIN3B." (PMID 39316363, 2024).
breast tumor (1 paper, 2023). "Collectively, these findings indicate that SIN3A and SIN3B phenocopy SAP30 to promote breast tumor angiogenesis, growth, and metastasis in vitro and in vivo." (PMID 37655663, 2023). "SIN3B, HDAC1, HDAC2, SUDS3, and RBBP4, but not SIN3A and SAP18, were also upregulated to a lesser degree in human breast tumors." (PMID 37655663, 2023).
ductal carcinoma in situ (1 paper, 2016). "In support of this, data analyzed from Oncomine revealed a trend towards decreased expression of SIN3A and increased expression of SIN3B in patients with triple negative invasive ductal carcinoma compared to ductal carcinoma in situ." (PMID 27780928, 2016).
glioblastoma (1 paper, 2025). The most malignant astrocytic tumor (WHO grade IV). "In mass-spec analysis using Sin3B, several DREAM complex components were identified as binding partners of the Sin3B–HDAC complex in T98G glioblastoma cells." (PMID 39796178, 2025).
pancreatic adenocarcinoma (1 paper, 2025). "Interestingly, the loss of the epigenetic factor SIN3B, which is involved in histone deacetylation, has been related to stromal activation of pancreatic adenocarcinomas." (PMID 40455824, 2025).
pancreatic ductal adenocarcinoma (1 paper, 2024). An infiltrating adenocarcinoma that arises from the epithelial cells of the pancreas.
thyroid carcinoma (1 paper, 2018). "Further annotation revealed that genes nearby H4K20me3/H3K4me3 marks are bound by OCT4, SETDB1, and SIN3B, are involved in DNA methylation, imprinting, gametogenesis, and sex determination, and are associated with thyroid carcinoma." (PMID 29969988, 2018).
triple-negative breast carcinoma (1 paper, 2016). An invasive breast carcinoma which is negative for expression of estrogen receptor (ER), progesterone receptor (PR), and human epidermal growth factor receptor 2 (HER2). "It is also interesting to note that expression of several SIN3A and SIN3B target genes in our data sets are consistent with the relapse-free survival identified for SIN3A and SIN3B for patients with triple negative breast cancer." (PMID 27780928, 2016). "Moreover, we identified correlations of high SIN3A and low SIN3B mRNA expression with relapse-free survival specifically in triple negative breast cancers." (PMID 27780928, 2016). "Overall, this data supports that SIN3A and SIN3B expression levels in cancer patients will depend on molecular subtype; and in triple negative breast cancer, lowered expression of SIN3A and higher expression of SIN3B may be associated with more aggressive disease progression." (PMID 27780928, 2016). "Interestingly, when analyzing triple negative breast cancers specifically, we noted that high SIN3A or low SIN3B mRNA expression correlated with longer relapse-free survival." (PMID 27780928, 2016). "However, high expression of SIN3A and low expression of SIN3B correlated with a longer relapse-free survival specifically in triple negative breast cancers (hazard ratios = 0.56 and 1.51; logrank P = 0.055 and 0.076 respectively for SIN3A and SIN3B)." (PMID 27780928, 2016).
tumor (6 papers, 2012 to 2025). "In the tumor microenvironment of PDAC, Sin3B‐deficient tumor cells and the recruitment of CD8+ T cells establish a positive feedback loop mediated by IFNγ‐CXCL9/10." (PMID 39316363, 2024). "In a murine PDAC model, we found that intrinsic loss of SIN3B within tumor cells enhances CD8+ T cell infiltration by increasing the secretion of IFNγ‐induced chemokines CXCL9 and CXCL10." (PMID 39316363, 2024). "Sin3B‐deficient tumor cells exhibited amplified CXCL9/10 secretion in response to Interferon‐gamma (IFNγ), creating a positive feedback loop via the CXCL9/10‐CXCR3 axis, thereby intensifying the anti‐tumor immune response against PDAC." (PMID 39316363, 2024). "Following this intervention, we noted that the CXCR3 blockade led to the abrogation of the anti‐tumor efficacy caused by Sin3B deficiency." (PMID 39316363, 2024). "To address this question, we sorted macrophages (CD45.2+F4/80+), CAFs (CD45.2−EpCAM−PDPN+), and tumor cells (CD45.2−PDPN−EpCAM+) from orthotopic tumors derived from control or Sin3B‐deficient groups." (PMID 39316363, 2024). "We observed a notable shift in immune cell infiltration upon loss of tumor cell‐intrinsic Sin3B, with a marked increase in total immune cells (CD45.2+) and a decrease in tumor cells (CD45.2−; EpCAM+)." (PMID 39316363, 2024). "In a cohort of surgical PDAC tumor samples from Renji Hospital (Renji Cohort 1), high SIN3B protein levels were associated with poor prognosis by Kaplan‐Meier survival analysis." (PMID 39316363, 2024). "Sin3B loss reshapes the tumor microenvironment, leading to increased infiltration as well as cytotoxicity of CD8+ T cells, to impede PDAC progression and enhance sensitivity to anti‐PD1 treatment." (PMID 39316363, 2024). "In vivo, tumor growth was rescued by specific knockdown of Cxcl9&10 in Sin3B‐deficient PDAC cells, accompanied by a significant decrease in tumoral infiltrating CD8+ T cells." (PMID 39316363, 2024). "Sin3B deficiency results in the upregulation of chemokines Cxcl9/10, thereby enabling the high levels of Cxcl9/10 in the tumor tissues to recruit more CXCR3‐expressing effector T cells." (PMID 39316363, 2024). "Further validation through RT‐PCR confirmed that tumor‐intrinsic loss of Sin3B resulted in a decrease in Cols expression in cultured PDAC cells, as well as in the orthotopic tumor tissues." (PMID 39316363, 2024). "Given the potential role of Sin3B deficiency on anti‐tumor immunity, we further investigated its role in modulating the tumor‐cell response to immunotherapy." (PMID 39316363, 2024). "Remarkably, Sin3B deficiency markedly inhibited tumor growth in C57BL/6J mice but only had minimal impact in NSG mice." (PMID 39316363, 2024). "Notably, our analysis of human PDAC tumor tissues revealed a consistent pattern, with lower levels of SIN3B associated with increased infiltration of CD8+ T cells." (PMID 39316363, 2024). "Given that Cxcl9 and Cxcl10 share the same receptor CXCR3, we hypothesized that Sin3B loss recruited CD8+ T cells into the tumor milieu predominantly through the CXCL9/10‐CXCR3 axis." (PMID 39316363, 2024). "Considering that the infiltration of immune cells into tumor tissues represents an active trafficking process driven by chemo‐attractants, we evaluated the levels of chemokines in both orthotopic and subcutaneous tumors derived from control or Sin3B‐deficient PDAC cells." (PMID 39316363, 2024). "Of note, Sin3B loss led to a slight increase in the absolute numbers of NKT, neutrophils, and dendritic cells (DC cells) infiltrating the tumor." (PMID 39316363, 2024). "Overall, our study identifies SIN3B as a potential therapeutic target for improving cytotoxic T cell accessibility to the tumor microenvironment and enhancing immunotherapy efficacy in the challenging context of PDAC." (PMID 39316363, 2024).